LATS2 (large tumor suppressor kinase 2)
Diseases named in the same sentence as LATS2 in open-access papers (continued):
Sharing a sentence is not in itself a finding about the gene and the disease.
tumor (continued). "Accordingly, we reveal that miR-31-5p plays an important role in the development of CRC and ultimately induces tumor growth and resistance in cancer cells by directly inhibiting LATS2 expression." (PMID 31623173, 2019). "LATS1 and LATS2 kinases are evolutionarily conserved tumor suppressors, which share ~50% and 85% amino acid sequence identity between the full proteins and the kinase domains, respectively." (PMID 31848340, 2019). "To further elucidate the underpinnings of LATS2-mediated tumor suppression, we analyzed the functional differences between the transcriptional profiles of Lats2-CKO PyMT and WT-PyMT tumors." (PMID 30456386, 2018). "Deletion of Lats2 in the mouse mammary gland results in increased lumB tumorigenesis and metabolic rewiring of the tumor cells." (PMID 30456386, 2018). "Human large tumour suppressor 2 (LATS2, also known as KPM), is a member of the LATS tumour suppressor family, and encodes a putative Ser/Thr protein kinase." (PMID 30046387, 2018). "In the current study, our findings showed that KLF2 and LATS2 functioned as a tumor suppressor in CCA." (PMID 29642935, 2018). "LATS2 is a key member of the Hippo pathway and functions as a tumor suppressor owing to its role in the suppression of cell growth and silencing the transcriptional co-activators YAP and TAZ." (PMID 29642935, 2018). "The four core components in this pathway comprise MST1 and MST2 kinases, SAV1 (also termed WW45), MOB1, and LATS1 and LATS2 kinases, all of which have been shown to act as tumor suppressors." (PMID 29565815, 2018). "We previously showed that lncRNA PVT1 is significantly upregulated in LAD tissues and cells, and that it promotes cell proliferation through epigenetically repressing tumor suppressor LATS2 expression by interacting with EZH2." (PMID 28109288, 2017). "And histological analysis of tumor sections and found that LATS2 upregulation and downregulation cells exhibited increased and decreased LATS2 protein staining in comparison to control groups, respectively." (PMID 29145896, 2017). "Recently, a considerable number of researches have grown up around the theme of miRNA/LATS2 axis involved in tumor development." (PMID 29145896, 2017). "Contrasting with these observations in other cancer types, our experiments demonstrated dramatic downregulation of LATS2 in ESCC tissues and cell lines, and a correlation between LATS2 expression levels and tumor metastasis and prognosis in ESCC patients." (PMID 29145896, 2017). "LATS2 is a well-established tumor suppressor that, under normal physiological conditions, can restrict cell proliferation and promote apoptotic cell death." (PMID 29108249, 2017). "Here, we showed for the first time that AGAP2-AS1 exerted oncogenic functions in human NSCLC cells by suppression of tumor suppressors LATS2 and KLF2." (PMID 27195672, 2016). "We also confirmed that CIT-K siRNA depletion activated the Hippo tumor suppressor pathway through phosphorylation of LATS2 in hTERT-RPE1 cells, as previously demonstrated in other cases of cytokinesis failure." (PMID 27895316, 2016). "Collectively, these results suggest the presence of a negative feedback mechanism in mouse liver that regulates YAP through LATS2 and exerts a tumor-suppressive function." (PMID 27006470, 2016).
tumor (continued). "It is worth noting that among the genes in Set A whose expression is down-regulated abound those with tumor-inhibitory activity (e.g., Pag1, PadI4, Lats2, and Cxcl3), while among the up-regulated genes are present tumor facilitators (e.g., Rab18, Dek)." (PMID 27965576, 2016). "Immunoblotting analysis of the implanted tumour tissues revealed increased Lats2 and p-Yap levels in Zyxin-knockdown tumours." (PMID 27030211, 2016). "Both LATS1 and LATS2 as tumor suppressors are part of hippo signaling pathway which has profound effects on normal cell fate and tumorigenesis." (PMID 26942001, 2016). "Cytokinesis failure leads to extra centrosomes that ultimately reduce RhoA activity in tetraploid cells, which in turn can activate the Large Tumor Suppressor Kinase 2 (LATS2) and the Hippo tumor suppressor pathway." (PMID 27731420, 2016). "The deletions of either LCD1 or LCD2 in mouse Lats2 abolished its tumor suppressor activity in immortalized mouse cell line." (PMID 25482410, 2015). "Reciprocally, activation of endogenous YAP and TAZ by depletion of LATS2 was sufficient to bypass the requirement for RasV12 to support anchorage independent growth in vitro and to support tumor formation in mouse xenograft assays (Fig2C)." (PMID 25180228, 2014). "The LATS2 expression was increased in the control cell tumors compared with that observed in the MIR31-expressing tumor cells, and the CCND1 levels were increased in the tumors formed from MIR31-expressing cells." (PMID 24779718, 2014). "It is plausible that MIR31 represses the expression of tumor suppressor genes, such as LATS2, to act as an oncomir and indirectly promotes the transcription of genes related to cell cycle control and tumorigenesis." (PMID 24779718, 2014). "The expression levels of LATS2 mRNA were also significantly up-regulated in three NPC tumor tissues, compared to the paired normal tissues." (PMID 20932276, 2010). "In the present study, LATS2 protein was found to be overexpressed in NPC tumor tissues and NPC cell lines." (PMID 20932276, 2010). "Our further retrospective tumor study showed that LATS2 protein was detected in 80.91% (178 of 220 cases) of NPC specimens." (PMID 20932276, 2010). "Methylation-specific PCR showed that LATS2 promoter methylation was present in 36.7% (11/30) NPC tumor tissues compared with 23 (100%) chronic nasopharyngeal inflammation epithelium samples." (PMID 20932276, 2010). "Through repressing tumor suppressors, LATS2 and PPP2R2A, miR-31 promotes cancer growth." (PMID 40332376, 2025). "Lats2, a central tumor suppressor and key kinase in the Hippo pathway, was induced by hyperoxia." (PMID 41516025, 2025). "Interestingly, YAP1-induced upregulation of LATS2 in HCvECs is a critical driver of this senescence process, which acts as a potent tumor-suppressive mechanism in normal cervical epithelial cells." (PMID 41256331, 2025). "Increased levels of LATS2 in the tumor tissue were connected to apoptosis." (PMID 37692482, 2024). "The tumor formation assay was conducted to examine the roles of melittin and LATS2 in vivo." (PMID 38889502, 2024). "Silencing MELK or EZH2 or overexpressing LATS2 suppressed tumour formation in nude mice." (PMID 38652219, 2024). "For instance, a specific tRNA half, 5′tiRNA-His-GTG directly targets the large tumor suppressor kinase 2 (LATS2) to curb the tumor-suppressive hippo signaling, which inhibits proliferation and promotes apoptosis by regulating Yes-associated protein (YAP) activity." (PMID 39659673, 2024). "Decreased expression of LATS1 or LATS2 leads to tumor enlargement and lymph node metastasis." (PMID 37548821, 2023). "In addition, they observed that miR-93 by targeting LATS2 supported tumor angiogenesis and invasion." (PMID 35499045, 2022). "The expression of LATS2 in tumours from each group was examined by qRT-PCR." (PMID 35902569, 2022).
tumor (continued). "However, KIBRA antibody, Merlin protein, and LATS1 and LATS2 kinase were slightly expressed in tumour cells (16.7%, 15.0%, and 15.0%, respectively)." (PMID 36552980, 2022). "The results confirmed that the tumor immunosuppressive environment of ESCC patients might be related to the relationship between LATS2 and PDL1 and CTLA4." (PMID 36118851, 2022). "Several Hippo pathway tumor suppressors, including Lats2, Mst1, and Mst2, were also slightly increased in Vgll4 mutant livers, consistent with the well-established negative feedback whereby activation of the nuclear effector YAP leads to up-regulation of upstream tumor suppressors." (PMID 36522128, 2022). "LATS2-mutated Y-MESO-27 cells were implanted into the mouse thoracic cavity and BIBR 1532 (2 mg/kg) was intraperitoneally administered twice-weekly after transplanting cells to investigate tumor growth and mouse survival." (PMID 36335095, 2022). "In addition, miR-93 was found to promote tumour angiogenesis and metastasis in breast cancer by suppressing tumour suppressor LATS2 expression, with increased lung metastasis demonstrated in a mouse model." (PMID 33477629, 2021). "Second, the underlying mechanisms for the association of LATS2 with tumor-infiltrating immune cells in CRC were not revealed." (PMID 34699318, 2021). "LATS2 is a protein that inhibits proliferation and encourages apoptosis in tumour cells." (PMID 33842488, 2021). "Furthermore, miR-372-3p, frequently overexpressed in CRC, targets LATS2 RNA, and its overexpression is correlated with tumour cell aggressiveness." (PMID 34885067, 2021). "Thus, the relationships between LATS2 expression and tumor-infiltrating immune cells were assessed by TIMER and ssGSEA." (PMID 34699318, 2021). "Univariate and multivariate analyses further confirmed that low LATS2 expression and advanced tumor stage could act as independent poor prognostic factors for CRC." (PMID 34699318, 2021). "Moreover, we identified the involvement of LATS2 in immune-related pathways and investigated its correlations with tumor-infiltrating immune cells." (PMID 34699318, 2021). "Our finding of LATS2 was consistent with its correlation with tumor stage and poor prognosis." (PMID 34824999, 2021). "miR-93 promotes tumor angiogenesis and metastasis by inhibiting the expression of LATS2." (PMID 34616746, 2021). "We determined the expression of LATS2 in tumor tissues by immunohistochemistry." (PMID 34699318, 2021). "The discrepancy may be due to several reasons, such as: different splicing forms of MT2A or LATS2 proteins may have different roles in tumor development; different lengths of patient follow-up used in the survival analysis may yield different HRs, etc." (PMID 33839701, 2021). "Furthermore, shRNA interfering actually retrieved the protein expression levels of LATS2 in the tumor xenografts." (PMID 33414893, 2020). "A recent study that used the cross-talk model of cell culture and medium supplemented with the serum of exercised women, showed that MCF-7 cells, but not MDA-MB-231 cells, had a suppressive effect of the physical exercise, mediated by the Lats2 tumor suppressor." (PMID 32151035, 2020). "LATS2 is a tumor suppressor that is homolog of Drosophila warts/lats." (PMID 33101546, 2020). "Interestingly, according to miRbase, miRanda, and TargetScan database analysis, LATS2, which inhibits the proliferation and migration of tumor via regulating the activity of YAP, is a direct target of miR-107." (PMID 32106857, 2020). "In addition, in xenograft tumours, we also confirmed that the expression of LATS2 and SAV1 was upregulated in the group treated with miR-103a-3p antagomir compared with the control group." (PMID 33218358, 2020).
tumor (continued). "LATS2 is a tumor suppressor that acts by phosphorylating downstream genes, such as YAP and TAZ." (PMID 31623173, 2019). "Next, we targeted LATS2 in tumor tissue to investigate whether miR-31-5p is involved in the mediation of OXA resistance and regulation of cancer growth." (PMID 31623173, 2019). "Moreover, immunohistochemical analysis suggested that the slower tumor growth rate and the reduced metastasis by miR-25 inhibition were, at least in part, due to the upregulation of LATS2 and E-cadherin expression and the downregulation of Vimentin and MMP9." (PMID 31316723, 2019). "Moreover, the miR-31-5p mimic inhibited the LATS2 pathway expression and promoted tumor growth in LoVo cells." (PMID 31623173, 2019). "LATS2 may inhibit cell and tumor growth, and the overexpression of LATS2 was found to significantly attenuate the role of oncogenic miRNA and vice versa." (PMID 31623173, 2019). "Additionally, miR-25 antagomir inhibited xenograft tumor growth and metastasis by the upregulation of LATS2." (PMID 31316723, 2019). "Importantly, we clarify the mechanism by which miR-31-5p expression not only decreases LATS2 expression and increases tumor growth but also enhances drug sensitivity." (PMID 31623173, 2019). "Typically in quiescent cells, Yap1 is phosphorylated downstream of the tumor suppressive Hippo pathway, by Lats1 and Lats2 kinases; phosphorylation leads to its sequestration in the cytoplasm by 14–3-3 proteins resulting in proteasomal degradation, thereby preventing its nuclear import." (PMID 30322398, 2018). "This led to the identification of 30 miRNA-mRNA interaction pairs involving known tumor suppressor targets of miR-21a-5p (Reck, Timp3 and Tgbr3) and miR-31-5p (Lats2 and Dmd) as well as oncogenic targets of miR-143-3p (Kras), miR-145-5p (Klf5, Kras) and miR-1195-5p (Met)." (PMID 30412601, 2018). "Together, such correlation between miR-363 and YAP1 translocation may confirm the mechanistic involvement of LATS2, as a tumour suppressor in TX-response." (PMID 30046387, 2018). "Altogether, this suggests that down-regulation of LATS1, but not LATS2, favors partial loss of luminal identity of tumor cells." (PMID 30456386, 2018). "Interestingly, in line with its tumor suppressive role, Lats2 expression declined progressively as WT-PyMT tumors became more aggressive." (PMID 30456386, 2018). "As a member of tumor suppressors, LATS2 could play a central role in the Hippo pathway in the inhibition of cell growth and tumor suppression." (PMID 29145896, 2017). "LATS2 is a component of the Hippo tumor-suppressive signaling pathway." (PMID 29145896, 2017). "LATS2 gene has been located onto chromosome 13q11–12, a hot spot region as a tumor suppressor." (PMID 29145896, 2017). "Furthermore, the role of LATS2 in tumor growth was examined using xenograft mouse models and uncovered that upregulation of LATS2 attenuated the tumor growth rate and reduced tumor volume in vivo." (PMID 29145896, 2017). "Furthermore, we determined that knockdown of AGAP2-AS1-mediated tumor-suppressive effects on NSCLC cells are partly dependent on regulation of LATS2 and KLF2 expression." (PMID 27195672, 2016). "We show that LIM domain protein Zyxin, as a scaffold protein, in response to hypoxia and TGF-β stimuli, forms a ternary complex with Siah2 and Lats2, thus stabilizes their interaction, and facilitates deactivation of the Hippo signalling, thereby promoting tumour progression." (PMID 27030211, 2016). "Taken together, our findings indicate that AGAP2-AS1 may act as an oncogene by repressing tumor-suppressor LATS2 and KLF2 transcription." (PMID 27195672, 2016). "Loss of the tumor suppressors NF2 and LATS2 have both been described in pleural mesotheliomas." (PMID 25798586, 2015).
tumor (continued). "Similarly, both Lats1 (−2.2-fold; p < 10−31) and Lats2 (−2.4-fold; p < 10−29), tumor suppressors that negatively regulate cell-cycle progression, showed a decrease in transcript levels." (PMID 25497456, 2015). "Firstly, deregulation of many proteins such as deficiency of myosin light-chain phosphorylation, overexpression of Aurora A, and mutation/inactivation of many tumor suppressers such as APC, BRCA1, and LATS2 could induce tetraploid cells." (PMID 22076149, 2011). "Overexpression of LATS2 in NPC tumor tissue is an indicator of poor prognosis in NPC patients." (PMID 20932276, 2010). "The present results differ from previously reported data on other malignant cancers, which showed a decrease in LATS2 mRNA levels in tumor tissue, implying that LATS2 may have different roles in different types of cells and/or cancers." (PMID 20932276, 2010). "The present work provides the first evidence of the overexpression of LATS2 in NPC tumor tissues." (PMID 20932276, 2010). "Furthermore, we found that in 36.7% of cases, the LATS2 promoter is methylated in NPC tumor tissues, while the LATS2 promoter was found to be methylated in all the chronic nasopharyngeal inflammation epithelium samples evaluated (100%)." (PMID 20932276, 2010). "Moreover, melittin suppressed tumor growth via up-regulation of LATS2 in vivo." (PMID 38889502, 2024). "The Hippo, PI3K/AKT, and tumor microenvironment signaling pathways, responsible for cell proliferation, migration, and invasion, were more enriched in differentially expressed predicted target genes (LATS2, NRAS, PPP2CB, etc.)in cells transfected with mimics of ISO-miR-1246_a and/or ISO-miR-1246_G." (PMID 38474054, 2024). "Furthermore, melittin decreased tumor growth and tumor weight when compared with the hypoxia group, LATS2 knockdown could reverse the impacts of melittin." (PMID 38889502, 2024). "We suspect that LEF1 recruits KDM4A/N-CoR and may recruit other epigenetic modification complexes to maintain the homeostasis of histone modifications at target promoters, thereby transcriptionally suppressing tumour-suppressor genes such as LATS2 and inhibiting the progression of OSCC." (PMID 37553362, 2023). "Furthermore, LATS2 was positively correlated with tumor-infiltrating immune cells." (PMID 34699318, 2021). "Notably, LATS2 expression had positive correlations with tumor-infiltrating immune cells, indicating that LATS2 may be associated with tumor immune infiltration in CRC." (PMID 34699318, 2021).